NRG4 (neuregulin 4)
Diseases named in the same sentence as NRG4 in open-access papers (continued):
Sharing a sentence is not in itself a finding about the gene and the disease.
diabetes (17 papers, 2016 to 2025). "The level of NRG4 in circulation was relatively high compared to prediabetic and diabetic patients and was an independent risk factor related to diabetes." (PMID 39280566, 2024). "As for clinical indices in diabetes patients, the glucose and adiposity parameters were positively associated with circulating Nrg4." (PMID 31815951, 2019). "However, the association between circulating Nrg4 levels and diabetes mellitus (DM) in human remains unclear." (PMID 31815951, 2019). "Thus, the purpose of this study was to evaluate the determinants and associations of plasma Nrg4 concentration with MetS characteristics, as defined by the Chinese Medical Association/Chinese Diabetes Society (CDS) diagnostic criteria, in newly diagnosed T2DM (nT2DM) patients." (PMID 29721105, 2018). "Several studies have identified elevated serum Nrg4 levels in patients with diabetes, while other studies have associated decreased serum Nrg4 levels with an increased risk of diabetes." (PMID 36703934, 2022). "These preclinical and clinical studies highlight Nrg4 as a promising therapeutic target and clinical predictive marker for diabetes and its complications." (PMID 36703934, 2022). "Observational studies comparing circulating Nrg4 levels in diabetes patients and health controls were included." (PMID 31815951, 2019). "Contrastingly, Chen demonstrated circulating Nrg4 levels was elevated in diabetes patients, similar results were concluded by Kang." (PMID 31815951, 2019). "A subgroup of cross-sectional study demonstrated that diabetes patients had higher circulating Nrg4 levels than their normal controls (SMD = 0.55, 95% CI = 0.36 to 0.73, P<0.001)." (PMID 31815951, 2019). "However, Logistic regression analysis showed that Asprosin and Nrg4 are still associated with T2DM-CHD after adjusting for factors such as age and diabetes duration." (PMID 36915073, 2023). "In patients with diabetes, NRG4 levels may be a good predictor of early detection of one or more diabetic microvascular complications." (PMID 36983737, 2023). "Most of these studies indicated that reduced serum levels of Nrg4 may play a substantial role in the development of diabetes." (PMID 36221104, 2022). "However, additional interventional studies should be performed to clarify the relevance of increased serum NRG4 in early diabetes." (PMID 36187779, 2022). "However, diabetes patients had higher circulating Nrg4 than their controls in cross-sectional studies (SMD = 0.55, 95%CI = 0.36 to 0.73, P<0.001)." (PMID 31815951, 2019). "Increased levels of NRG4 in situations of altered glucose tolerance or early diabetes, but decreased in those patients with advanced diabetes (as reflects increased microalbuminuria), suggest that NRG4 levels might depend on the evolution and stage of development of diabetes." (PMID 36187779, 2022). "Gluconeogenic activity is significantly impaired in diabetes, and hepatic Nrg4 was revealed in a study to play a crucial role in the regulation of gluconeogenesis in mice, suggesting that Nrg4 may serve as a potential target in diabetes." (PMID 36703934, 2022). "In summary, although our meta-analysis suggested circulating Nrg4 levels didn’t play a role in the process of DM, subgroup of the cross-sectional study revealed that circulating Nrg4 is higher in diabetes patients." (PMID 31815951, 2019). "Therefore, we speculate that Nrg-4 may be related to the pathogenesis of diabetes and CHD." (PMID 36915073, 2023). "These batokines including Nrg4 have been shown to improve metabolic diseases such as NAFLD, atherosclerosis, and diabetes." (PMID 36703934, 2022). "Eight weeks after the successful establishment of the diabetes model, the heart of the DM group was significantly larger than that of the CON group, but the enlarged heart phenotype was improved in the Nrg4 group (treated with Nrg4 in the last 4 weeks)." (PMID 36221104, 2022).
diabetes (continued). "Six studies presented data on the correlation coefficients of circulating Nrg4 levels and fasting plasma glucose (FPG) in diabetes patients, and five studies reported HOMA-IR." (PMID 31815951, 2019). "First of all, we evaluated the association of circulating Nrg4 levels with the risk of DM and glucose-related/non-glucose-related parameters in diabetes patients in the round, which added to the evidences on the role of circulating Nrg4 in human metabolism." (PMID 31815951, 2019). "In addition, the study also found the best cut-point value of Nrg-4 in clinical diagnosis of T2DM complicated with CHD, which has certain value in predicting whether diabetes is complicated with CHD." (PMID 36915073, 2023). "However, to date, there is no data on the role of Asprosin and Nrg-4 in diabetes and CHD." (PMID 36915073, 2023).
atherosclerosis (11 papers, 2016 to 2025). A disease characterized by the build-up of fatty material and calcium deposition in the arterial wall resulting in partial or complete occlusion of the arterial lumen. "In a mouse model, BAT-specific NRG4 deficiency exacerbated atherosclerosis, whereas restoring NRG4 levels reversed these effects, demonstrating its crucial role in maintaining vascular health." (PMID 40149686, 2025). "In concordance with these findings, a recent Mendelian randomization study found that elevated serum NRG4 plays a protective role in atherosclerosis, mediating lowered LDL-C levels linked to a reduced risk of peripheral atherosclerosis." (PMID 40149686, 2025). "BAT-specific NRG4 deficiency accelerates vascular inflammation, adhesion responses, endothelial dysfunction, apoptosis, and atherosclerosis in mice." (PMID 39872218, 2024). "In the current study, we aimed to explore the association between circulating Nrg4 and subclinical atherosclerosis in obese Chinese adults." (PMID 27819316, 2016). "Also, BAT-specific NRG4 deficiency accelerates vascular inflammation and adhesion responses, endothelial dysfunction and apoptosis and atherosclerosis in male mice." (PMID 40433407, 2025). "This community-based, cross-sectional study provided an opportunity to determine the role of circulating Nrg4 in predicting subclinical atherosclerosis." (PMID 27819316, 2016). "In conclusion, our study provides for the first time clinical evidence revealing that circulating Nrg4 concentrations are inversely associated with increased CIMT and atherosclerosis plaque in obese Chinese adults." (PMID 27819316, 2016). "NRG4 has been shown to decrease cardiac fibrosis, apoptosis, ferroptosis, oxidative stress, and atherosclerosis, while also inducing protective adaptations including increased mitochondrial function and enhancement of anti-inflammatory activity via Nrf2 signaling." (PMID 40149686, 2025). "The possible protective role of Nrg4 in subclinical atherosclerosis may involve indirect action, as well as a direct connection between this molecule and the cardiovascular system." (PMID 27819316, 2016). "In patients with T2DM and DPN, Nrg4 levels were negatively correlated with inflammation and oxidative stress markers hs-CRP, 88-iso-PGF2α, and VPT, suggesting that Nrg4 deficiency may trigger the development of atherosclerosis." (PMID 39162358, 2024). "However, information is not available regarding the association between circulating Nrg4 and subclinical atherosclerosis in humans." (PMID 27819316, 2016). "Additionally, our data indicated that circulating Nrg4 might have a cut-off value of 0.7 ng/ml for detecting subclinical atherosclerosis." (PMID 27819316, 2016). "Therefore, Nrg4 may become a novel therapeutic target for atherosclerosis disease." (PMID 38051471, 2024). "Evidence for the modulation of cardiovascular function exists in the context of pathological states, such as hypertension, atherosclerosis, and ischemia/reperfusion injury, for several of these batokines (FGF21, neuregulin 4, 12,13-diHOME, and BAT-derived microRNAs)." (PMID 40868154, 2025). "The underlying physiology of the relationship between NRG4 and CAD is not fully studied; NRG4 has an anti-apoptotic effect on endothelial cells and prevents the development of atherosclerosis." (PMID 32982804, 2020). "This narrative review focuses on four types of batokines (FGF21, neuregulin 4, 12,13-diHOME, and BAT-derived microRNAs) for which evidence of modulation of cardiovascular function exists in the context of pathological states such as hypertension, atherosclerosis, and ischemia/reperfusion injury." (PMID 40149686, 2025).
coronary artery disease (10 papers, 2020 to 2026). "Reduced levels of NRG4 have been reported to be associated with increased carotid intimal thickness, increased angiographic severity of coronary artery disease and acute coronary syndrome." (PMID 36071032, 2022). "In addition, NRG4 level was inversely associated with the severity of coronary artery disease (CAD)." (PMID 35056647, 2022). "Our findings demonstrate that engineered BA sheets exert potent cardioprotection against myocardial I/R injury by suppressing ferroptosis in an NRG4-ErbB4-dependent manner, supporting their promise as a therapeutic strategy for ischemic heart disease." (PMID 42206956, 2026). "Reduced levels of neuregulin 4 (NRG4) have been associated with increased carotid intima thickness, greater severity of coronary artery disease, and an increased risk of acute coronary syndrome." (PMID 40137134, 2025). "This was consistent in the case-control study where Nrg4 showed a significantly high area under the curve value (AUC, 0.85; 95% CI, 0.75 to 0.94) with 81.4% sensitivity and 95.3% specificity to identify coronary artery disease." (PMID 39162358, 2024). "Reduced NRG4 levels have also been observed in patients with coronary artery disease." (PMID 40149686, 2025). "Although the Nrg4 had 43.8% sensitivity and 96.9% specificity for identifying coronary artery disease, cross-sectional data showed that Nrg4 performed better in terms of sensitivity (73.1%) and specificity (87.3%) for identifying severe coronary artery lesions." (PMID 39162358, 2024). "Likewise, circulating Nrg4 levels were significantly reduced and negatively correlated with the presence and severity of the disease in patients with coronary artery disease." (PMID 39162358, 2024). "Circulating Nrg4 levels were inversely correlated with the presence and severity of coronary artery disease (CAD) and could be employed as a highly specific marker for identifying CAD presence." (PMID 36703934, 2022). "Circulating levels of Nrg4 were assessed in the serum and plasma of patients with T2DM-related macrovascular complications such as nephropathy and coronary artery disease." (PMID 39162358, 2024). "A negative correlation between circulating Nrg4 and the presence and severity of coronary artery disease was also reported in another study." (PMID 32477429, 2020).
breast carcinoma (6 papers, 2014 to 2026). "For instance, the administration of NRG4 may yield beneficial cardiometabolic effects but simultaneously increase the risk of breast cancer development through prolonged activation of the receptors ErbB3 and ErbB4." (PMID 39872218, 2024). "Collectively, these data in HER2+ breast cancer cells demonstrate that NRG4 activates ERBB4 and boosts the anti-proliferative effects of anti-ERBB2 agents." (PMID 35664762, 2022). "We thus suggest the administration of neuregulin 4 as a strategy to improve the efficacy of anti-ERBB2 neutralizing antibodies in breast cancer patients." (PMID 35664762, 2022). "HB-EGF and BTC were associated with poor clinical outcome and combined measurement of epigen and neuregulin 4 were predictors of relapse free and overall survival in breast cancer patients." (PMID 24952873, 2014). "Importantly, recombinant NRG4 (rNRG4) reduced the growth and invasiveness of breast cancer organoids." (PMID 41716632, 2025). "Collectively, our data in HER2+ breast cancer cells highlight that NRG1 may exert both pro- and anti-proliferative effects, and may reduce the efficacy of anti-HER2 agents, whereas NRG4 may boost the anti-proliferative effects of anti-ERBB2 agents." (PMID 35664762, 2022). "Our data suggest that the activation of ERBB4 by NRG4 does not have a significant impact on HER2+ breast cancer cell proliferation." (PMID 35664762, 2022). "Altogether, our data highlight that NRG1 may exert both pro- and anti-proliferative effects on HER2+ breast cancer cellular models, and may reduce the efficacy of anti-HER2 agents, whereas NRG4 consistently boosts the anti-proliferative effects of anti-HER2 agents." (PMID 35664762, 2022). "Importantly, treatment with NRG4 and simultaneous blockage of ERBB2, which is expected to specifically trigger the activation of ERBB4-ERBB4 homodimers, restrained the growth of HER2+ breast cancer cells more efficiently than anti-HER2 drugs alone." (PMID 35664762, 2022).
diabetic kidney disease (6 papers, 2020 to 2024). Progressive kidney disorder caused by vascular damage to the glomerular capillaries, in patients with diabetes mellitus. "NRG4 shows a strong association with preserved kidney function, alongside reduced mRNA expression in the adipose tissue of diabetic kidney disease (DKD) mice and a positive impact on glucose and lipid profiles." (PMID 38892221, 2024). "From these outcomes, it was concluded that combined detection of homocysteine/Nrg4 can be useful for early detection of diabetic nephropathy or diabetic kidney disease." (PMID 39162358, 2024). "Further study of the mechanism of how NRG4 plays a protective role in patients with diabetic nephropathy would be necessary for the future." (PMID 36983737, 2023). "A preclinical study found that Nrg4 expression was downregulated in rats with diabetic nephropathy and exerted therapeutic effects via TNF receptor one signaling." (PMID 36703934, 2022). "Another study similarly demonstrated decreased Nrg4 mRNA expression in adipose tissue in mice with diabetic kidney disease and significantly decreased circulating Nrg4 levels in human end-stage kidney disease, suggesting a potential protective effect of Nrg4 on kidney function." (PMID 36703934, 2022). "The AUCs predicted for diabetic nephropathy were Nrg4 (0.91, 95%CI: 0.859, 0.961), HCY (0.885, 95%CI: 0.822, 0.948), and homocysteine/NRG4 (0.961, 95%CI: 0.928, 0.994), respectively." (PMID 39162358, 2024).
acute coronary syndrome (5 papers, 2020 to 2025). Signs and symptoms related to acute ischemia of the myocardium secondary to coronary artery disease. "Accordingly, in the current study, we aimed to explore the relationship between serum Nrg4 levels and the risk of acute coronary syndrome (ACS) in Iranian CAD patients." (PMID 32242042, 2020). "Serum Nrg4 levels were significantly lower in acute coronary syndrome (ACS) and negatively correlated with HDL-C contents, a well-known beneficial lipoprotein, suggesting a possible association of serum Nrg4 levels with ACS prevalence." (PMID 36703934, 2022). "In the present study, we found a negative association between serum Nrg4 levels and the risk of acute coronary syndrome (ACS) (including acute myocardial infarction (AMI) + unstable angina pectoris (UAP)) but not stable angina pectoris (SAP)." (PMID 32242042, 2020).
colitis (5 papers, 2017 to 2023). Inflammation of the colon. "To test the impact of loss of NRG4/ErbB4 signaling specifically in macrophages during colitis, we used ErbB4myeKO mice." (PMID 33826403, 2021). "Here, we extended our previous findings by showing this loss of NRG4 occurs early in a model of acute colitis, and NRG4 levels are negatively correlated with TNF expression." (PMID 28230865, 2017). "To determine whether loss of NRG4 in colitis is driven by acute processes early in the injury/inflammation cycle, we analyzed colonic tissue from mice after 4 days of 3% (w/v) DSS exposure (injury phase) and 3 days post DSS (inflammatory phase)." (PMID 28230865, 2017). "We show that endogenous NRG4-ErbB4 signaling limits macrophage production of proinflammatory cytokines in vitro and limits colitis severity in vivo and thus is a potential target for therapeutic intervention." (PMID 33826403, 2021). "Treatment with its ligand NRG4 promotes macrophage apoptosis within 2 days and attenuates experimental colitis." (PMID 33826403, 2021). "Taken together, these findings demonstrate that NRG4/ErbB4 signaling in macrophages restrains the proinflammatory tone of these cells and is an important limiting regulator of colitis severity." (PMID 33826403, 2021). "Intriguingly, replacement of lost NRG4 with exogenous administration following induction of injury in DSS colitis to complete this circuit significantly attenuated inflammation and reduced colonic macrophage numbers." (PMID 28230865, 2017). "Consistent with this notion, NRG4 levels rebounded during the recovery phase, and administration of exogenous NRG4 during colitis reduced colonic macrophage numbers and ameliorated inflammation." (PMID 28230865, 2017). "The anti-inflammatory effect of Nrg4 was reported in experimental colitis mice." (PMID 32242042, 2020). "NRG4 expression was reduced at the injury phase with further downregulation observed during the inflammatory phase, indicating that NRG4 repression occurs early in colitis and is maintained throughout recruitment of inflammatory macrophages." (PMID 28230865, 2017). "As macrophages are the only myeloid cells on which we observed robust ErbB4 expression, together with our NRG4 rescue experiment results these findings support the idea that ErbB4 signaling in macrophages is a selective anti-inflammatory feedback mechanism in colitis." (PMID 28230865, 2017). "Third, confirming whether serum levels of ERBB2 and NRG4 were elevated in these patients was not possible because patients with germ cell tumors, colitis, and acute hepatitis, for which AFP is a false positive, were not included in this study." (PMID 37174100, 2023).
steatosis (5 papers, 2021 to 2025). Increased lipid within the cytoplasm of cells. "This contrasts with prior studies in high-fat diet-fed mice, where NRG4 reduced hepatic lipogenesis and improved steatosis." (PMID 40580113, 2025). "Liver-specific overexpression of c-FLIP in Nrg4 knockout NASH mice recovered inflammation and fibrosis levels, demonstrating the critical role of c-FLIP in the Nrg4-mediated progression of steatosis to NASH." (PMID 36703934, 2022). "Specialized themes also encompass the pink cluster as a niche theme regarding exercise-induced myokines such as neuregulin-4 (Nrg4), which mitigates steatosis via Nrg4/ErbB4/AKT signaling and demonstrates rapid effects on hepatic lipid metabolic reprogramming following sleeve gastrectomy." (PMID 40868109, 2025). "Interestingly, previous research has demonstrated the crucial role of hepatic Nrg4 signaling in the progression from steatosis to NASH." (PMID 38455470, 2024). "Nrg4 mRNA levels were significantly reduced in the adipose tissue of NASH mice, and Nrg4 knockout mice exhibited more severe liver fibrosis and inflammatory infiltration; interestingly, Nrg4 inhibition did not reduce steatosis in NASH mice." (PMID 36703934, 2022).